SCGB1D1 (secretoglobin family 1D member 1)
Description:
May bind androgens and other steroids, may also bind estramustine, a chemotherapeutic agent used for prostate cancer. May be under transcriptional regulation of steroid hormones.
Synonyms: LPNA; LPHA; LIPA; MGC71958
Tractability: Antibody: UniProt places it where antibodies can reach, with high confidence; UniProt predicts a signal peptide or a membrane-spanning region; its Gene Ontology location is reachable by antibodies, with medium confidence.
Gene: Protein-coding gene on chromosome 11 (62,190,216 to 62,193,539, forward strand). Ensembl gene ENSG00000168515.
Subcellular location: Secreted
Gene Ontology:
Molecular function: protein binding
Cellular component: extracellular region
Genetic constraint (gnomAD): Loss-of-function variants: 11 observed, 8.58 expected, observed/expected ratio (o/e) 1.28, 90% interval 0.8 to 1.87. That is too few expected variants to judge how well the gene tolerates losing a copy. Missense variants: 94 observed, 109.25 expected, observed/expected ratio (o/e) 0.86, 90% interval 0.73 to 1.02. Synonymous variants: 46 observed, 44.48 expected, observed/expected ratio (o/e) 1.03, 90% interval 0.82 to 1.32.
Homologues: Orthologues: chimpanzee SCGB1D1 (100% identical), macaque SCGB1D1 (93% identical), rabbit SCGB1D1 (57% identical), rabbit SCGB1D (52% identical), pig SCGB1D1 (49% identical), rat Scgb1d4 (44% identical), rat AABR07006242.1 (41% identical), rat Scgb1d2 (40% identical). Paralogues in human: SCGB1D2 (59% identical), SCGB1D4 (48% identical).
Diseases named in the same sentence as SCGB1D1 in open-access papers:
SCGB1D1 is named in the same sentence as 9 diseases in open-access papers, as found by Europe PMC text mining. Sharing a sentence is not in itself a finding about the gene and the disease. The quoted sentences say what the papers report.
lung carcinoma (1 paper, 2011). "The expression of SCGB1D1 (LIPA), SCGB2A1 (MGB2), and SCGB2A2 (MGB1) has been shown to be upregulated in human lung cancers." (PMID 21385388, 2011).
SCGB1D1 also shares sentences with these, for which no sentence is quoted: diabetic retinopathy (2 papers); Alzheimer disease (1); breast carcinoma (1); Graves’ orbitopathy (1); ovarian carcinoma (1); Parkinson disease (1); squamous cell carcinomas of the (1); tularemia (1).